SMAD7 (SMAD family member 7)
Diseases named in the same sentence as SMAD7 in open-access papers (continued):
Sharing a sentence is not in itself a finding about the gene and the disease.
Autoimmunity (3 papers, 2021 to 2024). The occurrence of an immune reaction against the organism's own cells or tissues. "miR-181c has been shown to enhance Th17 differentiation and promote autoimmunity through targeting Smad7 and modulating TGF-β pathway and IL-2 expression." (PMID 34804042, 2021). "Interestingly, cells in cluster 11 showed a distinct high expression of SMAD7 that in mice and humans have been associated with Th1 CD4+ T-cells involved in autoimmunity." (PMID 38287279, 2024).
colon adenocarcinoma (3 papers, 2008 to 2020). "In conclusion, we have established a mouse model for splenic injection of colon adenocarcinoma FET cells that develop liver metastasis when Smad7 is overexpressed." (PMID 18781153, 2008). "For this purpose, we have used splenic injection model of liver metastasis with colon adenocarcinoma-derived FET cells that stably express functional Smad7." (PMID 18781153, 2008). "We previously reported that overexpression of Smad7 in colon adenocarcinoma (FET) cells induces tumorigenicity by blocking TGF-β-induced growth inhibition and apoptosis." (PMID 18781153, 2008). "Previous study has suggested SMAD7 can induce growth and inhibit apoptosis in colon adenocarcinoma cells and acts as a tumor promoter, indicating that miR-581-mediated apoptosis might be SMAD7/TGFβ-pathway-independent." (PMID 32899503, 2020). "Smad7 overexpression could also induce liver metastases using splenic injection of nude mice with colon adenocarcinoma (FET) cells that had overexpression of Smad7." (PMID 22204639, 2011).
emphysema (3 papers, 2021 to 2025). "We have previously reported that acetylation of ProT and Smad7 is associated with emphysema progression." (PMID 40259641, 2025). "TGF-β overexpression is associated with early events during the emphysematous process, and TGF-β dysregulation due to acetylated Smad7 was shown to contribute to emphysema." (PMID 33535173, 2021). "ProT enhances Smad7 acetylation to stabilize Smad7 and inhibit TGF-β signaling, thereby contributing to the pathogenesis of emphysema." (PMID 34059951, 2021).
esophageal cancer (3 papers, 2017 to 2025). A primary or metastatic malignant neoplasm involving the esophagus. "CDCA7 promotes TGF-β-induced epithelial-mesenchymal transition to promote tumor progression by transcriptionally regulating Smad4/Smad7 in esophageal cancer cells." (PMID 39905019, 2025). "The expressions of hsa_circ_0001946 and circ-SMAD7 were downregulated in esophageal cancer cell lines." (PMID 31534563, 2019).
head and neck cancer (3 papers, 2016 to 2022). A primary or metastatic malignant neoplasm affecting the head and neck. "The cross-talk between TGF-β and NF-κB signaling pathways was mediated through TAK1 and SMAD7 in a subset of head and neck cancers." (PMID 36357371, 2022). "For example, in osteoclasts and head and neck cancers, TGFβ is found acting through the TGFβ activated kinase 1 to activate IKK and NF-κB, whereas NF-κB up-regulates SMAD7 to inhibit TGFβ signaling." (PMID 26946493, 2016). "In addition, p65-NF-κB activation induces SMAD7 expression and represses TGF-β/SMAD-regulated gene PAI1 in head and neck cancers." (PMID 31109359, 2019).
injury (3 papers, 2014 to 2021). Damage inflicted on the body as the direct or indirect result of an external force, with or without disruption of structural continuity. "In contrast to a transient increase in Smad7 in the activated HSC after acute liver injury, Smad7 remained at a low level in MFB throughout chronic liver injury." (PMID 26771649, 2016). "In contrast to a transient increase in Smad7 in the activated HSC after acute liver injury, Smad7 remains at a low level in MFB throughout chronic liver injury." (PMID 25050845, 2014). "In HSC after acute liver injury, TβRI activated by endogenous TGF-β signal phosphorylated Smad3C, further upregulating Smad7 transcription (right)." (PMID 25050845, 2014). "Subsequently, Smad7 terminates fibrogenic signals mediated by pSmad2L/C and pSmad3L/C and could be involved in the transient response to the autocrine TGF-β signal after acute liver injury." (PMID 26771649, 2016). "Subsequently, Smad7 terminates fibrogenic signals mediated by pSmad2L/C and pSmad3L/C, and could be involved in transient response to the autocrine TGF-β signal after acute liver injury." (PMID 25050845, 2014).
iron deficiency (3 papers, 2016 to 2019). "The HJV-BMP6-SMAD signaling pathway that normally activates the expression of hepcidin in iron deficiency is impaired by vitamin A deficiency despite increased expression of liver Bmp6 and Hfe2 mRNA levels and decreased expression of Smad7 mRNA." (PMID 27551308, 2016). "The down-regulation of hepatic Smad7 mRNA levels in the VAD group may reflect the inhibition of hepcidin by the systemic iron deficiency, as the levels of Smad7 and Hamp are coregulated in the liver." (PMID 27551308, 2016). "In conclusion, this study demonstrates that the HJV-BMP6-SMAD signaling pathway that normally activates the expression of hepcidin in iron deficiency is impaired by vitamin A deficiency despite increased expression of liver Bmp6 and Hfe2 mRNA levels and decreased expression of Smad7 mRNA." (PMID 27551308, 2016).
keratoconus (3 papers, 2017 to 2024). A degenerative, structural disorder of the eye, characterized by a cone-shaped protrusion of the cornea. "An additional study demonstrated that some of the downstream messengers in the TGF-β axis may be abnormal in keratoconus: KC keratocyte cell lines had downregulated expression of SMAD6 and SMAD7 when compared to normal keratocyte cell lines." (PMID 28932341, 2017).
kidney damage (3 papers, 2014 to 2023). "After 8 weeks of treatment, 24-hour urinary microalbumin (UAlb), urinary protein/urinary creatinine (Up/Ucr) values, ALT, AST, Bcr, kidney damage, TGF-β, Smad7, fibronectin (FN), and Smurf2 were detected." (PMID 24511554, 2014). "Additionally, miR-21 negatively regulates Smad7 to promote kidney damage and plays a role in promoting fibrosis via multiple pathways in nondiabetic nephropathies such as IgA nephropathy." (PMID 29038788, 2017).
kidney inflammation (3 papers, 2019 to 2024). "Tangshenfang can block activation of the NF-κB signaling pathway by inhibiting Smad7 and treat DKD kidney inflammation." (PMID 39312356, 2024). "Therefore, reasonable control of the level of Smad7 may be the key to the involvement of the TGF-β1/Smad3 and NF-κB signaling pathways in DKD kidney inflammation injury." (PMID 39312356, 2024).
lymphoma (3 papers, 2012 to 2020). A malignant (clonal) proliferation of B- lymphocytes or T- lymphocytes which involves the lymph nodes, bone marrow and/or extranodal sites. "TGF-β induces the expression of Smad7 in the murine interleukin-2 (IL-2)-dependent T-lymphoma cell line CTLL2, which has high expression of the transcription factor ZEB1 and low or no expression of Smad7." (PMID 32888405, 2020). "Instead, we found that overexpression of Smad7 is sufficient for lymphoma cells to become resistant to BMPs." (PMID 23049692, 2012). "Taken together, these results show that overexpression of Smad7 is sufficient for lymphoma cells to become resistant to BMPs." (PMID 23049692, 2012). "Importantly, we found that stable overexpression of Smad7 in BMP-sensitive lymphoma cells transformed them into BMP-resistant cells, showing that upregulation of Smad7 is sufficient for cancer cells to escape the negative effects of BMPs." (PMID 23049692, 2012). "Instead, we found that expression levels of inhibitory Smads varied across lymphoma cells, and that overexpression of Smad7 could transform highly BMP-sensitive cell lines to become BMP resistant." (PMID 23049692, 2012).
necrotizing enterocolitis (3 papers, 2021 to 2023). Necrotizing enterocolitis (NEC) is a devastating disease that affects mostly the intestine of premature infants. "Increased expression of Smad7 has also been seen in the gut of patients with necrotizing enterocolitis (NEC), an inflammatory bowel necrosis of premature infants." (PMID 33920230, 2021).
non-small cell lung carcinoma (3 papers, 2019 to 2022). A group of at least three distinct histological types of lung cancer, including non-small cell squamous cell carcinoma, adenocarcinoma, and large cell carcinoma. "On the other hand, miR-21-5p directly binds to SMAD7 mRNA, as evidenced by the luciferase assay in non-small cell lung cancer." (PMID 33147570, 2020). "Within non-small cell lung cancer, miR-21-5p inhibition enhanced cancer cell radiation sensitivity, while miR-21-5p overexpression promoted cell invasion and migration by targeting SMAD7." (PMID 36789695, 2022). "In non-small cell lung cancer cell lines, fucoidan stimulates the ubiquitin-dependent degradation in vitro of TGF-RI/II via Smurf2/Smad7." (PMID 30621045, 2019).
oral squamous cell carcinoma (3 papers, 2019 to 2021). "For its part, the deubiquitination enzyme CYLD is capable of inducing different tumor suppressor pathways, and its overexpression inhibits SMAD7-mediated cell invasion in oral squamous cell carcinoma (OSCC)." (PMID 33498521, 2021). "For example, miR-497 enhances metastasis of oral squamous cell carcinoma through SMAD7 suppression." (PMID 31370272, 2019).
osteoarthritis (3 papers, 2017 to 2022). A noninflammatory degenerative joint disease occurring chiefly in older persons, characterized by degeneration of the articular cartilage, hypertrophy of bone at the margins and changes in the synovial membrane. "The relationship between the predicted early posttraumatic osteoarthritis-associated miRNA, miR-181c-5p, and SMAD7 was verified." (PMID 35782228, 2022).
pituitary adenomas (3 papers, 2014 to 2022). "Reports have confirmed that SMAD7 can contribute to pituitary adenomas’ proceeding by activating the Wnt pathway." (PMID 35068324, 2022).
psoriasis (3 papers, 2021 to 2024). An autoimmune condition characterized by red, well-delineated plaques with silvery scales that are usually on the extensor surfaces and scalp. "The reduced expression of CD109 leads to diminished TGF-β signaling, leading to psoriasis by allowing increased Smad7 activity and subsequent inflammation." (PMID 39990858, 2024). "Moreover, different immunohistochemical studies found a correlation between psoriasis severity and Smad7 and Plexin-B2 expression." (PMID 38003284, 2023).
renal carcinoma (3 papers, 2018 to 2023). A carcinoma arising from the epithelium of the renal parenchyma or the renal pelvis. "Study has shown that the miR-452-5p expression is downregulated after sunitinib treatment and inhibits the migration and invasion of renal cancer cells by regulating the SMAD4/SMAD7 signaling pathway." (PMID 35465266, 2022). "Additionally, miR‐452‐5p promotes the invasion and metastasis of renal cancer cells by regulating the SMAD4/SMAD7 signaling pathways." (PMID 37014625, 2023).
triple-negative breast carcinoma (3 papers, 2020 to 2024). An invasive breast carcinoma which is negative for expression of estrogen receptor (ER), progesterone receptor (PR), and human epidermal growth factor receptor 2 (HER2). "To determine whether Smad7 is palmitoylated also in normal and malignant breast epithelial cells, we analyzed the human breast epithelial cell line MCF10A and the human triple-negative breast cancer cell line MDA-MB-231." (PMID 38876303, 2024).
acute kidney injury (2 papers, 2014 to 2022). Sudden and sustained deterioration of the kidney function characterized by decreased glomerular filtration rate, increased serum creatinine or oliguria. "Moreover, it has been reported that SMAD7 protects against acute kidney injury by rescuing the G1 cell cycle arrest of tubular epithelial cells." (PMID 35256739, 2022). "Consistently, our analysis detected the up regulation of SMURF1, suggesting it may contribute to the progression of renal failure through its ubiquitination of SMAD7." (PMID 24997640, 2014).
Adenovirus infections (2 papers, 2022). "Overexpression of Smad7 in AF cells with adenovirus infection was also successful." (PMID 35795857, 2022).
alcoholic liver damage (2 papers, 2011 to 2019). "SMAD7, a negative regulator of TGF-β signaling and hepcidin expression, when deleted from hepatic tissue, causes spontaneous liver injury and aggravates alcoholic liver damage." (PMID 31510077, 2019). "It is currently unclear whether endogenous Smad7 has an effect on liver function and alcoholic liver damage." (PMID 21386907, 2011).
alopecia (2 papers, 2021 to 2022). Hair loss usually from the scalp. "SMAD7 as an inhibitor of TGFβ signaling, was up-regulated in mice with alopecia, which was consistent with our findings in giant pandas with alopecia." (PMID 35413801, 2022).
Alzheimer disease (2 papers, 2024). A progressive, neurodegenerative disease characterized by loss of function and death of nerve cells in several areas of the brain leading to loss of cognitive function such as memory and language. "SMAD7 also demonstrates the strongest association with Neurobehavioral Disorders (NM), Alzheimer Disease (AD), and Stroke, while CCNB1 ranks second." (PMID 39840278, 2024).
Cachexia (2 papers, 2020 to 2023). Severe weight loss, wasting of muscle, loss of appetite, and general debility related to a chronic disease. "Winbanks exhibited this phenomenon through the delivery of Smad7 gene therapy in mouse models of cachexia, as Smad7 functions as an intracellular negative regulator, curbing the activation of Smad2 and Smad3 while promoting the degradation of ActRIIB complexes." (PMID 37755304, 2023). "SMAD7 prevents SMAD2/3 phosphorylation, promotes ActRIIB degradation, and was observed to increase muscle mass in healthy mice and attenuate wasting in models of cachexia." (PMID 33250771, 2020).
cholestasis (2 papers, 2009 to 2016). Impairment of the bile flow caused by obstruction within the liver, or outside the liver in the bile duct system. "Nevertheless, because of the strong effects of cholestasis, Smad7 was significantly downregulated in the miR-29aTg mice with cholestasis (p < 0.001)." (PMID 26938532, 2016).
Cognitive impairment (2 papers, 2023). Abnormal cognition is characterized by deficits in thinking, reasoning, or remembering. "The fear conditioning test showed that cognitive dysfunction postsurgery was attenuated significantly, suggesting that Smad7 overexpression in the hippocampus is heavily implicated in the occurrence of cognitive deficits after unilateral nephrectomy." (PMID 37507781, 2023). "The Smd7−/− mice exhibited significant improvement in learning and memory function after unilateral nephrectomy compared with the wild-type mice, further confirming that the elevation of Smad7 participated in cognitive impairment postoperation." (PMID 37507781, 2023). "The same results were observed in aged Smad7−/− mice, further confirming that Smad7 might be a promising therapeutic target for the clinical invention of cognitive impairment induced by anesthesia surgery." (PMID 37507781, 2023). "However, in the development of cognitive impairment postoperation, the elevated Smad7 interacts with TGF-β receptor type I, thus inhibiting the phosphorylation of Smad2/3." (PMID 37507781, 2023). "Our results revealed that Smad7 contributes to cognitive impairment after surgery by enhancing neuroinflammation and apoptosis in the hippocampus and might serve as a promising therapeutic target for the treatment of memory impairment after anesthesia surgery." (PMID 37507781, 2023). "However, little research has indicated the regulatory function of Smad7 in the development of cognitive impairment induced by anesthesia and surgery." (PMID 37507781, 2023). "Therefore, the aim of the present work was to determine whether Smad7 increases neuroinflammatory responses and apoptosis in the central nervous system and further mediates the occurrence of cognitive impairment after anesthesia and surgery." (PMID 37507781, 2023). "This leads to microglia activation and reduced Smad7–IkB pathway, which induces NF-κB nuclear translocation in neurons, increasing IL-1β which alters AMPA and NMDA receptors membrane expression, leading to cognitive impairment." (PMID 36593485, 2023). "Interestingly, the mice treated with shRNA–Smad7 preoperation exhibited longer freezing times than the mice treated with AAV vector or without treatment after unilateral nephrectomy, suggesting the involvement of Smad7 in the development of cognitive impairment induced by anesthesia and surgery." (PMID 37507781, 2023). "To evaluate whether Smad7 is involved in the occurrence of cognitive impairment after anesthesia and surgery by regulating the TGF-β1-related signaling pathway, we detected the protein expression of Smad2/3, Smad4 and phosphorylated Smad2/3 in the hippocampus in wild-type mice and Smad7−/− mice." (PMID 37507781, 2023).
COVID-19 (2 papers, 2022 to 2025). A disease caused by infection with severe acute respiratory syndrome coronavirus 2. "MiR-21-5p and miR-22-3p, both upregulated in COVID-19 patients, target several genes involved in cell signaling, cell proliferation and angiogenesis (e.g., HIF1A, MYC, SP1, SMAD7, VHL)." (PMID 36032130, 2022).
endometrial cancer (2 papers, 2021 to 2025). Primary or metastatic malignant neoplasm involving the endometrium (mucous membrane that lines the endometrial cavity). "Studies on endometrial cancer have shown that lncRNA MCTP1-AS1 regulates endometrial cancer cell proliferation, migration, invasion, and EMT processes through the miR-650/Smad7 axis." (PMID 40028033, 2025). "In conclusion, we show that hsa_circ_0001860 plays an important role in the resistance of EC to MPA through miR-520h/Smad7 axis, and it could be developed into a novel marker and therapeutic target for MPA-resistant endometrial cancer." (PMID 34912799, 2021).
gout (2 papers, 2023). A condition characterized by painful swelling of the joints, which is caused by deposition of urate crystals. "As a first exploration, mRNA levels of TGFB1, TGFBRI, TGFBRII and three TGF-β target genes ITGAV, MMP9 and SMAD7 were compared between untreated adherent monocytes of patients with gout and age and sex matched healthy controls." (PMID 36850003, 2023). "The CD4+ TCs and CD8+ TCs from gout remission were enriched in chemokines, such as CXCR4, as well as various antiinflammatory regulators (TNFAIP3, ZFP36, and SMAD7; an antagonist of TGF-β signaling)." (PMID 38063198, 2023).
head and neck squamous cell carcinoma (2 papers, 2020 to 2021). A squamous cell carcinoma that arises from any of the following anatomic sites: lip and oral cavity, nasal cavity, paranasal sinuses, pharynx, larynx, and salivary glands. "On the other hand, Smad7 also exerts an anti-inflammatory effect by inhibiting phosphorylation of IκBα and thus suppressing NF-κB-activated genes in human head and neck squamous cell carcinoma lines or in mouse skin." (PMID 33282009, 2020).
hyperglycaemia (2 papers, 2020). "We observed that increased miR‐21 may induce both cardiac mesenchymal fibrosis and cardiac perivascular fibrosis through SMAD7 signalling pathway and inhibition of miR‐21 decreased cardiac fibrosis induced by hyperglycaemia and prevented cardiac structural and functional abnormalities in T1DM mice." (PMID 31680453, 2020).
hypertensive cardiovascular disease (2 papers, 2013 to 2021). "Therefore, the present study investigated the role of Smad7 in hypertensive cardiopathy induced by angiotensin II infusion." (PMID 23894614, 2013).